ID3 (inhibitor of DNA binding 3)
Diseases named in the same sentence as ID3 in open-access papers (continued):
Sharing a sentence is not in itself a finding about the gene and the disease.
lymphoma (8 papers, 2015 to 2024). A malignant (clonal) proliferation of B- lymphocytes or T- lymphocytes which involves the lymph nodes, bone marrow and/or extranodal sites. "Five genes, all with variants in two cases, were shown to be associated with lymphoma pathogenesis (ID3, PAX5, TBL1XR1, IGLL5 and APC) in previous studies." (PMID 35205758, 2022). "Specifically, ∼2100 genes were differentially expressed in Id2- and Id3-deficient lymphomas versus Id2- and Id3-depleted CD4SP cells." (PMID 25691468, 2015). "We found that Id2- and Id3-deficient lymphomas revealed transcription profiles that overlapped with those derived from Id2- and Id3-deficient CD4SP cells." (PMID 25691468, 2015). "Collectively, these observations indicate that depletion of Id2 and Id3 in T-lineage cells leads to increased levels of morbidity caused by the development of lymphoma and/or inflammatory disease." (PMID 25691468, 2015). "In this regard, it is of interest that also in this disorder the clonally expanded rogue B-cells harbor mutations of lymphoma-related genes (CARD11, TNFAIP3, CCND3, ID3, BTG2, KLHL6)." (PMID 39055707, 2024). "Genes frequently mutated in BL are located in the BL-specific spot A (e.g. ID3, CCND3) and D (e.g. TCF3, SMARCA4, MYC) indicating their increased activity in BL and partly in intermediate lymphomas." (PMID 31039827, 2019). "Lymphomas depleted for Id2 and Id3 expression displayed elevated levels of c-myc, whereas p19Arf abundance declined." (PMID 25691468, 2015). "Collectively, these data point to a regulatory circuitry that underpins the mechanism by which Id2 and Id3 act to antagonize an innate variant TFH-specific program of gene expression, maintain thymocyte quiescence, and suppress the development of lymphoma." (PMID 25691468, 2015). "Together, the removal of H3K27me3 marks through PRC2 inhibition or depletion results in the upregulation of ACVR1 and the activation of BMP‐ACVR1 signaling, reflected by the phosphorylation of SMAD1/5 and the common upregulation of ID2 or ID3 in EZH2‐mutant lymphoma cells." (PMID 38229201, 2024). "In the setting of deregulated MYC, samples with ID3 mutations show a higher level of expression of known MYC target genes, and give rise to increased G1-to-S-phase cell-cycle progression in BL, suggesting a role for ID3 as a tumor suppressor in this type of lymphoma." (PMID 32102485, 2020). "How do lymphomas develop in Id2- and Id3-depleted thymocytes?" (PMID 25691468, 2015). "Skewing towards the E47 expression seems to be particularly pronounced in BL as compared to other mature GCB-lymphomas and, thus, likely contributes to deregulation of the TCF3/ID3 complex particularly in BL lacking ID3 and/or TCF3 mutations." (PMID 30926794, 2019).
pancreatic cancer (8 papers, 2007 to 2023). "Reduced expressions of Id-1 and Id-3 have been demonstrated to inhibit the metastatic ability of gastric cancer cells, and Id-1 expression has been shown to be associated with the presence of invasion in endometrial carcinoma and tumour angiogenesis in human pancreatic cancer." (PMID 18000500, 2007). "Knockdown of ID1 and ID3 inhibited metastatic potentials of esophageal and pancreatic cancers in vitro and in vivo." (PMID 23768125, 2013). "The role of ID1, ID2 and ID3 are expected to be oncogenic due to their overexpression in pancreatic cancer and colorectal adenocarcinomas, respectively." (PMID 18513385, 2008). "ID1, ID2 and ID3 are overexpressed in several human tumour entities, e.g. pancreatic cancer and colorectal adenocarcinomas." (PMID 18513385, 2008). "Similarly, the combined inhibition of Id1 and Id3 in human pancreatic tumor cells resulted in decreased ability of pancreatic cancer cells to proliferate and migrate." (PMID 23311395, 2013). "Similarly, other studies have shown that simultaneous targeting of Id1 and Id3, compared to targeting of each gene alone, is more effective at inhibiting tumor growth and metastatic potential of breast, colorectal, gastric, and pancreatic cancers." (PMID 19956687, 2009). "Furthermore, the IL-7R, PLD4, and ID3 markers were statistically significant both in the univariate and multivariate models for differentiating pancreatic cancer from non-pancreatic cancer." (PMID 37165046, 2023).
Obesity (7 papers, 2014 to 2025). Accumulation of substantial excess body fat. "Together these evidences implicate ID3 as a molecular risk factor of obesity susceptible to environmental disruption especially to EEDs that accumulate in the fat tissue." (PMID 29507860, 2018). "This study concluded that the loss of ID3 prevented HFD-induced obesity via inhibiting VEGFA expression and adipose tissue angiogenesis necessary to support the expansion of visceral fat." (PMID 29507860, 2018). "This review will discuss the current understanding of ID3 in excess fat accumulation and the potential for EEDs to influence susceptibility to obesity or metabolic disorders via ID3 signaling." (PMID 29507860, 2018). "Furthermore, increases in expression of the SERPINE1 and ID3 genes, which are associated with obesity, and a decrease in pro-inflammatory CCL2 gene expression highlighted the impact of mechanical stretch on the cholesterol biosynthesis pathway." (PMID 32759460, 2020). "Furthermore, we extended this understanding of how ID3 and metabolic perturbations by environmental factors such as EEDs can increase the risk of obesity." (PMID 29507860, 2018). "Although we cannot rule out the contribution of ER signaling and aromatase activity in the promotion of adipogenesis by EEDs, we propose that ID3 may be an additional molecular risk factor for obesity from environmental exposure to estrogenic chemicals." (PMID 29507860, 2018). "Therefore, ID3 mediated metabolic programming of mitochondria may be dysregulated by exposure to EEDs and increase susceptibility to obesity." (PMID 29507860, 2018). "In addition, the ID3 dependent production of adipocytokines and recruitment of macrophages in adipose tissue are suggested to play an important role in the inflammatory process to enhance susceptibility to obesity or metabolic complications." (PMID 29507860, 2018). "Genes downregulated in SHBG-stimulated adipocytes included LEP, LEPR, FLST3, CRTC2, and ID3, all of which are known to contribute to obesity-induced inflammation and insulin resistance." (PMID 40532849, 2025). "Specifically, we identified an increased expression of the miR-224 targets Ndufa11, Cox17, Cox16b1, and Id3 in BAT, which associate with metabolic syndrome and obesity." (PMID 34342596, 2021). "Specifically, we postulate that EEDs can induce ROS-mediated ID3 phosphorylation and acetylation, histone acetylation, and DNA base oxidation collectively that control expression of ID3 target genes involved in obesity and metabolic programming." (PMID 29507860, 2018). "ID3 is known to regulate the production of IL-5, IL-6, IL-8, and IL-10 which have been observed in population studies of obesity and/or MetS." (PMID 29507860, 2018). "Genetic studies have demonstrated that the transcriptional regulator ID3 promotes high fat diet-induced obesity in vivo." (PMID 29507860, 2018). "This review is focused on linking the obesogenic effects of EEDs to ID3 signaling leading to increased fat accumulation or obesity." (PMID 29507860, 2018). "ID3 mediated gene regulation governing these processes in adipocytes and stem/progenitor fat cells provides a possible explanation for how ID3 promotes high fat diet-induced obesity in the experimental model." (PMID 29507860, 2018). "Genetic studies have demonstrated that the transcriptional regulator inhibitor of differentiation-3 (ID3) promotes high fat diet-induced obesity in vivo." (PMID 29507860, 2018). "Epigenetic imprinting of adipocyte progenitor or fat stem cells by ID3 in the maternal programming of obesity shown in offspring exposed to EEDs is another plausible mechanism based on the following evidence." (PMID 29507860, 2018). "The contribution of ID3 to vasculogenesis, energy metabolism, and the immune system make it a unique molecular factor to study in obesity because it cuts across these complex organ systems." (PMID 29507860, 2018).
Obesity (continued). "In vivo studies have demonstrated that ID3 mediates high fat diet-induced obesity and promotes obesity-induced inflammatory macrophage accumulation." (PMID 28785583, 2017). "Taken together, these lines of evidence provide the basis for how ID3 can participate in metabolic perturbations via controlling the expression of inflammatory factors involved in obesity and/or MetS." (PMID 28785583, 2017). "Several studies indicate a novel role for ID3 as a regulator of obesity." (PMID 29507860, 2018). "HFD-induced obesity was shown to be reduced in ID3−/− knockout (ID3 KO) compared to wild-type mice." (PMID 29507860, 2018). "Several lines of evidence suggest that ID3 mediated inflammation may contribute to obesity through an imbalance in pro- and anti-inflammatory factors secreted by fat cells." (PMID 29507860, 2018). "ID3 has been shown to promote obesity in experimental models of HFD-induced obesity." (PMID 29507860, 2018). "The Inhibitor of DNA Binding/Differentiation-3 (ID3), a member of the ID family of transcriptional regulators, has been shown to play a role in adipogenesis and therefore ID3 may influence obesity and metabolic health in response to environmental factors." (PMID 28785583, 2017). "ID3 may contribute to metabolic syndrome via its effects on obesity because animal models have already shown that ID3-induced visceral fat expansion in mice fed a high-fat diet." (PMID 25090023, 2014). "Taken together, EEDs through induction of ROS may increase histone acetylations by posttranslational activation of acetylases and oxidation of DNA bases, which are necessary for ID3-mediated transcription regulation of target genes involved in obesity and metabolic complications." (PMID 29507860, 2018). "Hence, ID3 KO prevented the observed increase in obesity from exposure to the HFD." (PMID 29507860, 2018). "Since ID3 is a transcription regulator of genes involved in both cell proliferation and stemness, EEDs may facilitate the uncontrolled proliferation of adipocytes through ID3 contributing to obesity or metabolic disorders." (PMID 29507860, 2018). "Hence, Id3 KO mice may be protected from HFD-induced obesity due to the absence of adipocyte progenitor cells and/or high levels of p21Cip1." (PMID 29507860, 2018).
colorectal cancer (6 papers, 2015 to 2026). A primary or metastatic malignant neoplasm that affects the colon or rectum. "Our prior investigation has demonstrated that ID3 modulates PD-L1, thereby affecting immune evasion in colorectal cancer (CRC)." (PMID 41486422, 2026). "This study aimed to investigate the relationship between ID3 and radiosensitivity in colorectal cancer cell lines through in vivo and in vitro experiments." (PMID 37170184, 2023). "At the same time, a xenograft tumor model of HCT116 cells in nude mice was established to study the effect of irradiation on the tumorigenesis of ID3 knockdown colorectal cancer cells in vivo." (PMID 37170184, 2023). "ID3 interacted with PPARγ and form a positive feedback loop to enhance the effect of ID3 on the radiosensitivity of colorectal cancer." (PMID 37170184, 2023). "When ID3 is increased, it inhibits PPARγ protein, and when PPARγ is inhibited by ID3, it further promotes ID3 expression, to gradually enhance the malignancy of colorectal cancer cells and radiotherapy resistance." (PMID 37170184, 2023). "To clarify the specific mechanism of ID3 in reducing the radiosensitivity of colorectal cancer cells, we detected the expression of ID3 and DNA damage repair proteins MDC1 and γH2AX after irradiation by western blotting." (PMID 37170184, 2023). "Once PPARγ was inhibited by ID3, it further promoted ID3 and formed a positive feedback loop to gradually enhance the malignancy of colorectal cancer cells and radiotherapy resistance." (PMID 37170184, 2023). "In conclusion, through communication with MDC1, ID3 and PPARγ formed a positive feedback loop to promote the repair of DNA damage, thus affecting the radiosensitivity of colorectal cancer cells." (PMID 37170184, 2023). "We found that when colorectal cancer cells were exposed to irradiation, ID3, γH2AX, and MDC1 increased and formed foci to repair DNA damage caused by irradiation." (PMID 37170184, 2023). "Co-immunoprecipitation and immunofluorescence were performed to analyze the possible mechanism of ID3 in the radiosensitivity of colorectal cancer." (PMID 37170184, 2023). "ID3 and PPARγ influence the radiosensitivity of colorectal cancer cells by interacting with MDC1 to form a positive feedback loop that promotes DNA damage repair." (PMID 37170184, 2023). "Emerging evidence indicates that the increased expression of Id1 and Id3 is positively correlated with the self-renewal and tumor-initiation abilities of colorectal cancer-stem cells." (PMID 26965643, 2016). "Thus, the role of ID3 in the radiosensitivity of colorectal cancer has been further highlighted in this study." (PMID 37170184, 2023). "Our study also verified the role of ID3 in the radiosensitivity of colorectal cancer in vivo." (PMID 37170184, 2023). "Thus, ID3 is very important for the radiosensitivity of colorectal cancer cells." (PMID 37170184, 2023). "ID3 can be induced by calcium-binding protein S100A8 and inhibits p21 to regulate the cell cycle and proliferation of colorectal cancer cells." (PMID 37170184, 2023). "Meanwhile, immunofluorescence also showed that ID3, MDC1, and γH2AX foci were increased in colorectal cancer cells after irradiation." (PMID 37170184, 2023). "To study the effect of ID3 on the radiosensitivity of colorectal cancer cells, we constructed ID3 knockdown and control cell lines HCT116-NC, HCT116-ID3 KD, HT-29-NC, HT-29-ID3 KD, and ID3 overexpression cell lines and control cell lines HCT116-PC, HCT116-ID3 OE, HT-29-PC, and HT-29-ID3." (PMID 37170184, 2023).
colorectal cancer (continued). "Furthermore, ID1, but not ID3 expression, was also found to be on average threefold higher (and up to ninefold higher) in PBMCs from patients with metastatic breast cancer (n=7) and colorectal cancer (n=6) compared with healthy, age-matched controls (n=10, Mann–Whitney test; P<0.01)." (PMID 25924227, 2015).
depression (6 papers, 2017 to 2023). "Psychopathologies such as anxiety and depression have been associated with ID3 methylation status." (PMID 28785583, 2017). "In traumatized children, increased methylation in three genes (NMDA glutamate receptor, GRIN1; inhibitor of DNA binding 3, ID3; and tubulin polymerization promoting protein, TPPP) was associated with reduced rates of depression." (PMID 30781888, 2019). "Methylation in four genes developed as predictors of depression: ID3, NMDA, GRIN1, and TPPP." (PMID 30081481, 2018). "In the epigenome study of children, methylation at CpG sites in DNA-binding protein inhibitor ID-3 (ID3), tubulin polymerization promoting protein (TPPP), and Grin1 were inversely related to depression severity in maltreated children." (PMID 35865627, 2022). "Results showed that methylation in three genes were considered significant predictors of depression, including Tubulin Polymerization Promoting Protein (TPPP), DNA-Binding Protein Inhibitor-3 (ID3), and Glutamate N-Methyl-d-Aspartic Acid Receptor (GRIN1)." (PMID 30634536, 2019). "Behavioral differences in the EPM and FST tests showed that these genes, ID3, GRIN1, and TPPP, could predict anxiety and depression." (PMID 28785583, 2017).
gastric cancer (6 papers, 2007 to 2025). A primary or metastatic malignant neoplasm involving the stomach. "Further investigation is justified to clarify the precise molecular mechanisms by which miR-214-3p dysregulation impacts the 3’UTR length and expression of the ID3 gene, as well as its broader role in gastric cancer progression." (PMID 41318488, 2025). "The number of peritoneal metastases is significantly reduced, and the size of single metastases is also decreased, which proves that Id1 and Id3 knockout can significantly inhibit peritoneal metastasis of gastric cancer cells." (PMID 23900621, 2013). "These regulatory mechanisms could influence the length of 3’UTRs and, consequently, the expression of target genes, including ID3, in the context of gastric cancer progression." (PMID 41318488, 2025). "Co-suppression of ID1 and ID3 significantly reduces proliferation, invasiveness, anchorage-independent growth, and angiogenesis and increases apoptosis in small-cell lung cancer; moreover, targeting ID1 and ID3 reduces the formation of peritoneal metastases by gastric cancer cells." (PMID 34295890, 2021). "We obtained 43 DEGs with the adjusted p < 0.05 and | log2 FC)|>1, of which JUNB, ID1, CDKN1C, ID3, and BCAR3 were lowly expressed in gastric cancer tissues, and the remaining DEGs were highly expressed in gastric cancer tissues." (PMID 36467074, 2022).
Sjögren’s syndrome (6 papers, 2016 to 2023). "Similar to the clinical manifestations of primary Sjogren's syndrome, Id3-deficient mice serve as useful dry eye models for primary Sjogren's syndrome." (PMID 35178415, 2022). "As our results showed Id3 depletion enhance the immunoregulatory role of BMMSCs, combining with our previous study have showed the impaired immunoregulatory role of BMMSCs in NOD/ShiLtJ mice, the increased Id3 levels of BMMSCs would be a pathogenic factor induced a Sjögren’s syndrome." (PMID 32139667, 2020). "This indicated that the Sjögren’s syndrome in Id3 knockout mouse was majorly involved by Th2 cells." (PMID 32139667, 2020). "Id3−/− mice develop many symptoms similar to those found in Sjögren’s syndrome, like immune cells chronically attack the lachrymal and salivary glands, resulting in impaired tear and saliva secretion." (PMID 32139667, 2020). "Id3 homozygous null mice have been reported to induce features of Sjogren's syndrome, a chronic autoimmune disease, which disrupts salivary and lachrymal glands." (PMID 27805903, 2016). "Id3 pathway may be involved, because some authors have found that Id3 knockout mice develop many symptoms like those found in Sjogren’s syndrome." (PMID 37629654, 2023). "These include OAS1, C4A, and IFIH1 for Type 1 diabetes and ID3 and C4 for Sjögren’s syndrome." (PMID 30002654, 2018). "For instance, it will be useful to understand whether depletion of TAZ in Id3−/− mice relieves the symptoms of Sjogren's syndrome." (PMID 27805903, 2016).
viral infection (6 papers, 2015 to 2022). "Further unbiased investigation into the most expressed genes per cluster revealed a plethora of genes previously reported in the context of viral infections, such as Il7r, Tcf7, Zeb2, Klrg1, Gzma, Gzmb, Gzmk, Vim, Lgals3, Tox, Lag3, Pdc1, Id3." (PMID 35185882, 2022). "In activated T cells, Usp1 interacts with Id2 and Id3, protects the stability of Id2 protein in the context of viral infection, and maintains the proliferative potential and memory phenotype differentiation of virus-specific CD8 effector T cells." (PMID 35983065, 2022). "Importantly, within the Th1 compartment, we identified a subset of Id3-GFPhi cells that appeared as early as day 7 of acute viral infection and accumulated in frequency as the Th1 compartment contracted but were consistent in numerical quantity over time." (PMID 35858332, 2022). "For CD8 T cells, a recent study discovered that Tcf1 directly modulates the expression of Id3, which is important for both effector and central memory function of CD8 T cells, thereby affecting optimal CD8 T cell activity in the context of viral infection." (PMID 35983065, 2022).